MIR4697 (microRNA 4697)
Synonyms: hsa-mir-4697
Gene: MicroRNA gene on chromosome 11 (133,898,504 to 133,898,581, reverse strand). Ensembl gene ENSG00000284020.
Diseases named in the same sentence as MIR4697 in open-access papers:
MIR4697 is named in the same sentence as 1 disease in open-access papers, as found by Europe PMC text mining. Sharing a sentence is not in itself a finding about the gene and the disease. The quoted sentences say what the papers report.
ovarian carcinoma (1 paper, 2017). A malignant neoplasm originating from the surface ovarian epithelium. "Herein, we investigated the role of a long noncoding RNA named MIR4697 host gene (MIR4697HG) in the cell growth and metastasis of ovarian cancer." (PMID 28168162, 2017).